PDCD1 (programmed cell death 1)
Diseases named in the same sentence as PDCD1 in open-access papers (continued):
Sharing a sentence is not in itself a finding about the gene and the disease.
cancer (continued). "Our findings highlight that the roles of PDCD1 expression and nsSNPs vary according to the cancer type." (PMID 40149458, 2025). "The B7/CD28 family of molecules, comprising several immune checkpoint proteins and their receptors, such as CD28, CTLA4, PDCD1, etc. have gained considerable attention in the field of cancer therapy." (PMID 40808941, 2025). "Monoclonal antibodies such as ipilimumab, durvalumab, and nivolumab target cytotoxic T lymphocytes associated antigen 4 (CTLA-4) and programmed cell death 1 (PD1) and its ligand (PDL1) to increase T-cell activity in cancer treatment." (PMID 40481994, 2025). "CNIH4 was also observed to be significantly positively correlated with multiple immune checkpoints, including CD276, CD86, and PDCD1, in cancers such as KIRC, KIRP, and LGG." (PMID 40051704, 2025). "TIGIT, LAG3, PDCD1, and CXCL13 were highly associated with different stages of cancers, especially in KIRC and THCA." (PMID 40076932, 2025). "Immune checkpoint inhibition (CPI) trials with other cancers have mainly focused on antibody-targeting programmed cell death 1 protein (PD-1), programmed cell death ligand 1 (PD-L1) and cytotoxic T-lymphocyte antigen-4 (CTLA-4)." (PMID 40563565, 2025). "Combining Irg1 knockdown via small interfering RNA (siRNA) with OVA mRNA in LNPs augmented the therapeutic efficacy of mRNA cancer vaccines, both as monotherapy and in combination with an anti-programmed cell death-1 antibody." (PMID 40521193, 2025). "Cancer immunotherapy has transformed the treatment of cancer, with a success of immune checkpoint inhibitors of programmed cell death 1 and its ligand." (PMID 40254425, 2025). "Consistent with murine studies, well-known Tex genes (CTLA4, LAG3, HAVCR2 (gene encoding Tim-3), PDCD1, TIGIT, TOX) were among the most prominently represented in Tex from human cancers." (PMID 40236693, 2025). "Streptococcus increases the response of anti-Programmed cell Death 1 (PD-1)/PD- ligand 1 (L1) by inducing the wetting of CD8+ T cells in cancer tissues." (PMID 40475781, 2025). "Immune checkpoint inhibitors (ICIs) targeting programmed cell death-1 (PD-1), programmed death ligand-1 (PD-L1), and cytotoxic T-lymphocyte-associated protein 4 (CTLA-4) have revolutionized cancer therapy by restoring antitumor immunity." (PMID 41463041, 2025). "Programmed death-ligand 1 (PD-L1, CD274), an immune checkpoint protein expressed on cancer cells and immune cells, interacts with its binding partner programmed cell death-1 (PD-1) to inhibit T cell proliferation and cytokine production." (PMID 39335579, 2024). "One dramatic example includes complete gray hair reversal as a side effect of cancer therapy (e.g., anti-programmed cell death 1 (anti-PD-1) and anti-programmed cell death ligand 1 (anti-PD-L1) therapy for lung cancer)." (PMID 38182857, 2024). "Immune checkpoint inhibitors (ICIs) that target the programmed cell death 1 (PD-1)/programmed cell death ligand 1 (PD-L1) axis have been developed to improve the cancer immunity cycle." (PMID 39108499, 2024). "For this, we combined the anti-DBI/ACBP mAb with chemoimmunotherapy (which is the current standard of care for many cancers, i.e., chemotherapy together with immunotherapy targeting PDCD1) against two types of cancers, namely NSCLC and cutaneous sarcoma." (PMID 39419485, 2024). "Third, DBI/ACBP neutralization ameliorates the outcome of cancer treatments with chemotherapy and immunotherapy targeting PDCD1." (PMID 39419485, 2024). "The landscape of cancer treatment has witnessed a transformative shift with the advent of immunotherapies, notably the programmed cell death 1 (PD-1)/PD-1 ligand (PD-L1) checkpoint blockade." (PMID 39528472, 2024). "Clinically, it has been confirmed that immune checkpoint inhibitors, especially programmed cell death 1 (PD-1) antibody therapy, are effective in various cancers." (PMID 38510750, 2024).
cancer (continued). "Background/Objectives: Immune checkpoint blockade, particularly targeting the programmed cell death 1 (PD-1) receptor, is a promising strategy in cancer immunotherapy." (PMID 39449324, 2024). "Remarkably, five genes (PDCD1LG2, CD48, IDO1, LAIR1, and PDCD1) were found to be present in both the cancer-immunity cycle inhibitors and checkpoint genes categories." (PMID 38540734, 2024). "PD-L1 is a major co-inhibitory checkpoint protein that is highly expressed in various cancers and can bind to programmed cell death 1 (PD-1) on T cells to control T cell activity and is currently the main cause of immune escape of tumor cells." (PMID 39014462, 2024). "Further exploratory analyses revealed that CTLA4, PDCD1, and the cancer antigens MSLN, MUC1, EPCAM, and PROM1 presented significantly increase expression levels in the high-risk subtype group." (PMID 39712016, 2024). "The programmed cell death 1 (PD-1) and programmed cell death ligand 1 (PD-L1) axis play a key role in physiological immune homeostasis and can serve as a means for cancer cells to evade the immune system." (PMID 38361936, 2024). "The use of immunosuppressants targeting programmed cell death ligand 1 (PD-L1) and/or programmed cell death 1 (PD-1) in particular heralds an entirely new age of immunotherapy in cancer treatment." (PMID 38549936, 2024). "Immune checkpoint inhibitors (ICIs) targeting programmed cell death 1 (PD-1) and programmed cell death ligand 1 (PD-L1) have revolutionized cancer treatment in the recent years, affording long-term survival benefit in a broad range of cancer patients." (PMID 38400933, 2024). "As expected, C5aR expression was found to result in high T cell dysfunction scores in various cancer types, surpassing even the well-known T cell exhaustion-inducing markers, programmed cell death 1 (PDCD1) and programmed cell death-ligand 1 (PDL1)." (PMID 38098230, 2024). "One of the key immune checkpoints in cancer treatment is the programmed cell death 1 (PD1) receptor, mainly expressed on the surface of T cells." (PMID 38902345, 2024). "Cancer immunotherapy with monoclonal antibodies blocking the inhibitory programmed cell death-1 pathway (PD-1/PD-L1) significantly improved the survival of patients with TNBC." (PMID 37919269, 2023). "A paradigm shift has occurred in the management of non-small-cell lung cancer (NSCLC) due to advances in cancer immunotherapy, including immune checkpoint inhibitors (ICIs) that target programmed cell death-1 (PD-1) and programmed cell death-ligand 1 (PD-L1)." (PMID 37601658, 2023). "Previous studies have shown that cancers defined as ‘hot tumors’ (many infiltrating T cells and high expression of PD-L1/PDCD1) are more responsive to ICI treatment." (PMID 36941725, 2023). "Recent advancements in immunotherapy, which boosts antitumor activity using cytotoxic T-lymphocyte antigen 4 (CTLA-4), programmed cell death-1 (PD-1), and PD ligand 1 (PD-L1) inhibitors, have altered the therapeutic approach for a variety of cancers." (PMID 37214445, 2023). "Immune checkpoint inhibitors (ICIs), which inhibit programmed cell death 1 (PD-1) or programmed cell death 1 ligand 1 (PD-L1) and cytotoxic T lymphocyte-associated protein 4 (CTLA-4), have shown success in treating many cancers." (PMID 38066642, 2023). "Nivolumab is an immune checkpoint inhibitor that targets the programmed cell death-1 protein and is effective in treating advanced cancer." (PMID 36997886, 2023). "As a newcomer to cancer treatment, programmed cell death 1 (PD-1) blockade-based immunotherapy exploits a strategy based on immune evasion mechanisms to restore antitumor immunity." (PMID 37355621, 2023). "Overall, use of immune checkpoint inhibitor (ICI) therapies targeting the cytotoxic T lymphocyte (CTLA-4) or programmed cell death ligand 1 (PD-L1)/programmed cell death-1 (PD-1) pathway represents a major breakthrough for a number of cancers." (PMID 37587505, 2023).
cancer (continued). "By interacting with programmed cell death 1/ligand 1(PD-1/PD-L1) and cytotoxic T lymphocyte-associated antigen 4 (CTLA-4), ICIs prevent cancers from escaping from antitumor immune response, leading to significant improvement in clinical outcome." (PMID 37124234, 2023). "Immunotherapy has demonstrated its great potential in the treatment of a variety of cancers, particularly through immune checkpoint inhibitors targeting PDCD1/ CD274." (PMID 36979400, 2023). "Immunotherapy with programmed cell death 1 (PD-1) checkpoint inhibitors combined with chemoradiotherapy shows great potential for cancer treatment and is getting extensively researched." (PMID 38312255, 2023). "The PD-L1 protein will bind with the programmed cell death-1 (PD-1) protein expressed on activated T cells to suppress T-cell-mediated attacks on cancer cells." (PMID 37371564, 2023). "Its binding to LAG3 results in T cell depletion, mechanisms of immune evasion of the cancer and resistance to anti-PDCD1/CD274 therapy." (PMID 37215135, 2023). "We next examined the associations of TLR4 expression with 8 immune checkpoints (PD-L1, CTLA4, HAVCR2, LAG3, PDCD1, PDCD1LG2, SIGLEC15, and TIGIT), and TLR4 expression was widely associated with the 8 immune checkpoints in most cancer types." (PMID 37576399, 2023). "In the era of immunotherapy, programmed cell death 1 (PD−1)/PD−ligand 1 (PD−L1) has been shown to be a biomarker for cancer diagnosis and prediction of response to immunotherapy, but is not sufficiently sensitive." (PMID 36979667, 2023). "PD1-related checkpoints were highly related to pyroptosis activities in different cancer types, including Programmed Cell Death 1 (PD-1, PDCD1), Programmed Cell Death 1 Ligand 1 (PD-L1, CD274), and Programmed Cell Death 1 Ligand 2 (PDCD1LG2)." (PMID 37863886, 2023). "Programmed cell death-ligand 1 (CD274, PD-L1), which can be expressed on the surface of cancer cells binds to programmed cell death protein 1 (PDCD1, PD-1) on an immune cell surface, which inhibits immune cell activity." (PMID 38022653, 2023). "Programmed cell death-ligand 1 (PD-L1) is expressed on cancer cells and interacts with programmed cell death-1 (PD-1) which is expressed on activated lymphocytes, thereby inducing exhaustion and apoptosis of the activated lymphocytes." (PMID 37646826, 2023). "Recent cancer immunotherapies targeting immune checkpoint inhibitors (ICIs) such as anti-programmed cell death-1 (PD-1) and anti-programmed cell death ligand-1 (PD-L1) antibodies have led to durable remission across a wide variety of different cancer types." (PMID 37835397, 2023). "K-M survival analysis indicated that OS and PFS were better in cancer patients treated with PDCD1, CD274, and CTLA4 with elevated KLRB1 expression." (PMID 37988189, 2023). "Cancer cells frequently exploit the Programmed Cell Death 1 (PD-1) signalling pathway to evade immune surveillance." (PMID 37691915, 2023). "Treatment with the mTORC1 inhibitor everolimus, which is currently in clinical trials for T-NHL therapy (NCT00918333 and NCT01075321), reduced viability and division of PDCD1-mutant cancer cells." (PMID 37723306, 2023). "Over the past few decades, research on cancer immunotherapy using immune checkpoint inhibitors (ICIs) targeting the programmed cell death-1 (PD-1)/programmed cell death-ligand 1 (PD-L1) pathway has achieved remarkable progress." (PMID 37190284, 2023). "Immune checkpoint blockade with monoclonal antibodies targeting the programmed death-ligand 1 (PD-L1)/programmed cell death 1 (PD-1) pathway or cytotoxic T lymphocyte-associated antigen 4 (CTLA-4) prolonged patient survival, considering many cancer types." (PMID 37627082, 2023). "PDCD1 is closely associated with TMB, MSI, and immune cell infiltration, and can be used as a prognostic marker in various cancers." (PMID 37178414, 2023).
cancer (continued). "Cancer-derived EVPs expressing PD-L1 block antitumor immunity by interacting with programmed cell death-1 (PD-1) on immune cells, reducing the efficacy of immune checkpoint inhibitors (ICBs)." (PMID 38707985, 2023). "The programmed cell death 1 (PD-1) receptor is a premier immune checkpoint target for cancer immunotherapy." (PMID 35864188, 2022). "Another means by which cancer cells evade T cell immune surveillance is via binding to the programmed cell death 1 (PD-1) protein." (PMID 35814431, 2022). "Anti-programmed cell death 1 (PD-1) and anti-cytotoxic T-lymphocyte-associated protein 4 (CTLA4) checkpoint inhibitors have known efficacy in MSI-H cancers, as well as TMB-high cancers." (PMID 35267592, 2022). "Immune checkpoint inhibitors that can target CTLA-4 and the programmed cell death 1 (PD-1)/programmed cell death ligand 1 (PD-L1) axis induce significantly enhanced therapeutic responses in cancer immunotherapy." (PMID 36145656, 2022). "In contrast, Pdcd1 overexpression in cancer cells promotes the induction of apoptosis, which is further enhanced by DOX." (PMID 35190965, 2022). "Some ICIs block the interaction between programmed cell death-1 (PD-1) on T cells and its ligand PD-L1 on cancer cells and myeloid cells 4-6." (PMID 36046644, 2022). "Immune checkpoint blockade (ICB) therapies that target programmed cell death-1 (PD-1)/programmed cell death-ligand 1 (PD-L1) pathway are currently used for the treatment of various cancer types." (PMID 35647515, 2022). "It is possible that Pdcd1 signaling promotes apoptosis in cancer cells, while it has anti-apoptotic properties in cardiomyocytes." (PMID 35190965, 2022). "Immune checkpoint inhibitors (ICIs), which target programmed cell death 1 (PD-1) and its ligand (PD-L1), are capable of inducing sustained antitumor effects, ushering in the therapeutic era for multiple malignant neoplasms." (PMID 36338995, 2022). "Immune checkpoint inhibitors (ICIs) targeting the programmed cell death-1 (PD-1)/programmed cell death-ligand 1 (PD-L1) pathway are the standard therapeutic options for cancer patients." (PMID 35524214, 2022). "In most cancer types, SERCA3 expression was also associated with immune checkpoints, including PDCD1 and CTLA-4." (PMID 36385955, 2022). "The programmed cell death 1 (PD-1)/(PD-1 ligand) PD-L1 has been reported to be an effective indicator in cancer development." (PMID 35619918, 2022). "Somewhat similar, both trials rely on the CRISPR/Cas9 gene editing of the human PD1 gene or a multiplex strategy to edit TRAC, TRBC, and PDCD1 genes in autologous T-cells extracted from cancer patients in order to enhance the antitumor effect." (PMID 35159110, 2022). "Combining CRISPR/Cas9 with CAR-T cells and PD-1, the editing PDCD1 gene in T cells was an ideal method to cure cancer." (PMID 35935840, 2022). "Programmed death-ligand 1 (PD-L1), an immune checkpoint protein expressed on cancer cells and immune cells, interacts with its binding partner programmed cell death-1 (PD-1) to inhibit T cell proliferation and cytokine production." (PMID 35890277, 2022). "We also examined the effects of Pdcd1 overexpression on the DOX-induced apoptosis of human cancer cell lines K562 and MCF-7." (PMID 35190965, 2022). "Immunotherapies, especially the programmed cell death 1/programmed cell death ligand 1 (PD-1/PD-L1) inhibitors, have revolutionized the therapeutic strategies of various cancers." (PMID 36159842, 2022). "We also assessed the correlations between DAAM2 and the expression of immune checkpoints, including TIGIT, CTLA4, CD274, and PDCD1, across cancers." (PMID 35281277, 2022). "CD274, PDCD1, and CTLA-4 were known as critical immune checkpoints that are associated with immune escape in cancers." (PMID 36254230, 2022). "Our findings brought to light that PTX3 had a close and positive association with most ICIs (CD274, CTLA4, HAVCR2, LAG3, PDCD1, PDCD1LG2, TIGIT, and SIGLEC15) in TCGA cancers, except TGCT." (PMID 36139597, 2022).
cancer (continued). "The immune checkpoint blockade (ICB) therapy, which specifically targets the cytotoxic T lymphocyte antigen 4 (CTLA-4) and programmed cell death 1 (PD-1) or its ligands (PD-L1), has been used for cancer immunotherapy and has shown promising clinical results." (PMID 36591468, 2022). "In the contemporary era, cancer immunotherapy, which blocks the programmed cell death-1 (PD-1)/programmed death-ligand 1 (PD-L1) axis, is a novel treatment approach in a variety of malignancies." (PMID 36387259, 2022). "The interaction between programmed cell death ligand-1 (PDL-1) and its receptor, programmed cell death 1 (PD-1), inhibits T cell responses, making EVs effective for immunotherapy of different cancers." (PMID 35139852, 2022). "Especially, high expression of LAG3, CTLA4, PDCD1 (PD-1), IDO1, and CD274 (PD-L1) were widely reported to be associated with suppressive immune response and suppressed T cell function in cancer." (PMID 35902970, 2022). "Rat cardiomyocyte cell line H9c2 and human cancer cell lines K562 and MCF-7 were transfected with Pdcd1-encoding plasmid DNA to establish Pdcd1-overexpressing cells." (PMID 35190965, 2022). "Cancer treatment has been radically altered by programmed cell death-ligand 1 (PD-L1) inhibitors and programmed cell death 1 (PD-1) over the last few decades." (PMID 35049699, 2022). "Recent studies in a variety of epithelial cancers have shown that PDCD1 is presented in infiltrating immune cells and PD-L1 is expressed on cancer cells." (PMID 35431930, 2022). "Immunotherapy targeting cytotoxic T lymphocyte antigen 4 (CTLA4), programmed cell death-ligand 1 (PD-L1), or programmed cell death 1 (PD-1) have become effective and frequently-used ways in the treatment of various cancers." (PMID 35711939, 2022). "Anti-programmed cell death-1 (PD-1) therapy exerts beneficial effects in a limited population of cancer patients." (PMID 36261600, 2022). "Another remarkable finding of this study is that the overexpression of Pdcd1 in cancer cells promoted apoptosis induction, which was further enhanced by DOX." (PMID 35190965, 2022). "Meanwhile, combined therapy of SOAT1 inhibitor avasimibe plus programmed cell death 1 antibody was found to have an enhanced therapeutic effect in controlling some cancer growth in mice." (PMID 34914638, 2022). "Anti-programmed cell death-1/programmed cell death-ligand 1 (PD1/PD-L1) antibody is approved for the first or second line of treatment for various cancers." (PMID 35892331, 2022). "SNX-482 was also shown to upregulate the expression of CCR4 (C-C motif chemokine receptor 4), IFNG (IFN-gamma), GZMB (granzyme B) and PDCD1 (programmed cell death protein 1) genes, which are important for anti-cancer activity." (PMID 36119523, 2022). "In recent years, immunotherapy, especially immune checkpoint inhibitors (ICIs) targeting programmed cell death-1 (PD-1) and its ligand PD-L1, has revolutionized cancer treatment and substantially improved patient outcomes in NSCLC." (PMID 36437916, 2022). "Immune checkpoint molecules, such as programmed cell death-1 (PD-1) and PD-L1, allow cancer cells to proliferate by inhibiting cytolytic T cell (CTL) and natural killer (NK) cell activity." (PMID 36076996, 2022). "Programmed death protein 1 (PD-1, encoded by the PDCD1 gene) and its ligand programmed death-ligand 1 (PD-L1, encoded by the CD274 gene) function in the immunotherapy of cancer by evading T cell immunity." (PMID 36499447, 2022). "CTLA4 and PDCD1 genes are two representative immune checkpoint genes, proven to have an excellent immune blocking effect in various cancers." (PMID 35281840, 2022). "Our results revealed that high LMS was positively associated with the expression of CTLA4, PDCD1, TIGIT and GZMB in the EC and pan-cancer cohorts." (PMID 35834061, 2022). "Monoclonal antibodies (mAbs) targeting the programmed cell death 1 (PD-1) receptor or its ligand PD-L1 are increasingly used for the treatment of multiple forms of cancer, especially solid tumors." (PMID 35884428, 2022).